KRAS (KRas proto-oncogene, GTPase)
Diseases named in the same sentence as KRAS in open-access papers (continued):
Sharing a sentence is not in itself a finding about the gene and the disease.
colon carcinoma (continued). "Future studies using organoid models in conjunction with in vivo studies could help further address the differential dependencies for proximal vs. distal colon cancer development, as well as for KRAS and BRAF mutation-driven tumorigenesis." (PMID 38360902, 2024). "Despite the high frequency of observed KRAS gene mutations, primarily in pancreas, lung, and colon cancer, RAS (K-, N-, H-) gene mutations are also widely prevalent in many other cancer types, which led to the notion that they contribute to oncogenesis in approximately 20% of human cancers." (PMID 39455841, 2024). "In addition, right-sided colon tumors, which have increased prevalence of KRAS and BRAF mutations and are associated with worse prognosis compared to left-sided colon tumors, respond poorly to EGFR inhibition." (PMID 38672633, 2024). "Therefore, the specific link between KRAS mutation and goblet cell accumulation and differentiation in colon cancer needs to be further examined in future studies." (PMID 36349418, 2023). "Almost 50% colon cancer patients were reported bearing KRAS mutation." (PMID 37670977, 2023). "In addition, KRAS oncogene mutations are relatively common in the formation of colon cancer, and direct targeted therapy of the KRAS gene is ineffective." (PMID 37020597, 2023). "In colon cancer, somatic KRAS mutations, located mainly in codon 12 and 13 of exon 2, have been reported to lead to a more aggressive and invasive tumor and have been associated with resistance to anti-epidermal growth factor receptor (EGFR) monoclonal antibodies such as cetuximab and panitumumab." (PMID 36900260, 2023). "Interestingly, combinational treatment of 5-florouracil and IL-1RA decreases the proliferation ability in colon cancer cells with KRAS mutation." (PMID 37461111, 2023). "KRAS is one of the leading mutations reported in colon cancer." (PMID 38097680, 2023). "Despite the higher prevalence of the KRAS mutation in patients with right-sided colon cancers, it cannot be considered that the presence of the mutation alone could explain the worse prognoses of these patients." (PMID 36836752, 2023). "Therefore, the combination of PLK1 inhibitor and MEK inhibitor is promising to remove the resistance of MEK inhibitor, which will provide a new therapeutic target for KRAS-mutated colon cancer." (PMID 37020597, 2023). "In colon cancer, KRAS, NRAS, BRAF and PIK3CA were the well-known driver mutations." (PMID 37670977, 2023). "Therefore, the Inhibition of MAPK and PI3K pathway is an effective treatment for KRAS-mutated colon cancer." (PMID 37020597, 2023). "Furthermore, there is a limited role of other molecular mutations as biomarkers in predicting the response of colon cancer to immunotherapy; this includes KRAS mutation, a common molecular subtype in colon cancer." (PMID 36483562, 2022). "A high intake of PUFA, in particular linoleic acid, may be an important dietary risk factor for KRAS mutated colon tumors, possibly by generating G > A transitions or G > T or G > C transversions in the KRAS oncogene." (PMID 36344948, 2022). "KRAS mutations are known to be involved in the early stages of colon cancer carcinogenesis." (PMID 36083889, 2022). "Therefore, determining the KRAS mutation status of tumors is a significant step in managing patients with colon cancer." (PMID 36591510, 2022).
colon carcinoma (continued). "Interestingly, specific repression of Furin in colon tumors induced by cancer cells with KRAS or BRAF mutation inhibited the expression of Nanog and LGR5 compared to wild-type KRAS and BRAF developed tumors." (PMID 35267511, 2022). "Mutations in KRAS are among the most frequent aberrations in cancer, including colon cancer." (PMID 35456940, 2022). "Studies have reported that BRAF mutations and KRAS mutations are independent and exclusive of each other, account for 5–15% of metastatic colon cancers, and are associated with poor prognosis in advanced colon cancer." (PMID 35479956, 2022). "The KRAS gene mutation at codon 12 is a common mutation in colon cancer." (PMID 36109734, 2022). "Consistent with this hypothesis, we observed a lower number of KRAS mutations detected in high-BMI colon cancer patients." (PMID 36046651, 2022). "Intriguingly, unlike previous reports, the direct identification of neoantigens with a representative cancer driver mutation, an oncogenic KRAS, from the terminal stage of colon cancer tissue was achieved by an established DIM-MS-based global-immunopeptidomics approach." (PMID 35982173, 2022). "Since KRAS and BRAF gene mutations are frequently present in colon cancers, we asked whether KRAS and BRAF mutations were more prevalent in GALNT6-negative tumors." (PMID 35692787, 2022). "Considering the high rate (~30%) of KRAS mutations in colon cancer, we thereby hypothesize that the functions of KRAS may vary in different tumor microenvironments, and further investigation is urgently needed." (PMID 35563733, 2022). "Indeed, droplet digital PCR (ddPCR) using evDNA was able to detect KRAS G12D and G13D mutations in colon cancer and demonstrated a comparable association with CEA and OS, which reflects the clinical status of patients." (PMID 36591510, 2022). "KRAS G12C is one of the most prevalent oncogenic driver mutations in lung and colon cancer." (PMID 36099883, 2022). "In colon cancer, KRAS mutations are present in 30–50% of patients." (PMID 35118074, 2021). "KRAS, a frequently mutated gene in colon cancer was found mutated in both cell lines." (PMID 34066331, 2021). "In a recent study of patients with KRAS G12C mutated colon cancer, it was shown that comprehensive analyses of gene expression profiles, co-occurring alterations of other genes and protein expression might shed light on the involvement of signalling pathways." (PMID 34503114, 2021). "For this purpose, they used KRAS mutated human colon cancer cells." (PMID 34781949, 2021). "Together, these findings provide new perspective on the protective role of cancer-derived exosomes, which may aid in the improvement of the therapeutic approach to targeting KRAS mutation in colon cancers." (PMID 33466836, 2021). "KRAS-activating mutations are present in more than 40% of patients with colon cancer." (PMID 34485153, 2021). "Previous studies have shown that KRAS activating mutation is associated with enhanced cell migration in invasion activities in many types of cancer, such as pancreatic ductal adenocarcinoma, prostate cancer, colon cancer, and breast cancer." (PMID 34956887, 2021). "The recent finding that KRAS mutations in LUAD may serve as a potential predictor for guiding anti-PD-1/PD-L1 immunotherapy needs to be further validated in colon cancer." (PMID 34485153, 2021).
colon carcinoma (continued). "In addition, KRAS mutations are closely associated with alterations in ROS production and mitochondrial metabolism in colon cancer cells." (PMID 34203665, 2021). "Thus, for patients with BRAF- or KRAS-mutated colon cancer, alternative targeted treatment strategies still need to be developed." (PMID 34885128, 2021). "Approximately 40% of colon cancers are positive for mutations in KRAS." (PMID 33348563, 2020). "The fact that women tend to have more right-sided colon cancers, and KRAS is more frequently mutated in these cancers, could make the interpretation of sex differences in KRAS more complex." (PMID 33363037, 2020). "According to the authors, ascorbic acid combined with cetuximab may impact the MAPK/ERK signaling pathway, which is disturbed in colon cancers with a KRAS mutation." (PMID 33352824, 2020). "Red meat consumption may increase colon cancer risk by inducing the endogenous production of N-nitroso compounds and their precursors, which may induce KRAS mutations." (PMID 32723394, 2020). "Next, we examined whether growth of KRAS‐mutated and wild‐type KRAS colon cancer cells is dependent on glutamine." (PMID 31709772, 2020). "Hence, it is interesting to evaluate the anti-cancer potential properties of the 1,4-pentadiene-3-one on colon cancer cells carrying KRAS mutation and exhibit molecular phenotypes of chromosomal instability (CIN) that accounts 85% of all sporadic CRCs." (PMID 32825505, 2020). "KRAS is the isoform commonly mutated in the pancreas, lung, and colon cancers." (PMID 32703218, 2020). "However, two recent independent studies showed that covalent inhibitors of KRAS with G12C mutations led to regression of lung and colon tumors in clinical trials." (PMID 32545208, 2020). "Besides, stage 2 colon cancer patients with KRAS mutation were also reported to have increased risk of recurrence which was not affected by adjuvant chemotherapy." (PMID 32859214, 2020). "This suggests that colon tumors with the particular genetic profile of RKO (BRAF mutated) may benefit most from the potential applications of VPE in anti-colon cancer strategies than KRAS mutated HCT116-like tumors." (PMID 32806531, 2020). "Based on this finding, it could be postulated that HT29 and Caco-2 colon cancer cells (with wild-type KRAS) are more sensitive toward MUM265 extract than colon cancer cell SW480 (with mutated KRAS oncogene) which was resistant toward MUM265 extract." (PMID 30760201, 2019). "We previously demonstrated that BTK is an actionable target in KRAS-mutated colon cancer." (PMID 31200752, 2019). "This concept was directly tested in the study of colon cancer cells overexpressing GLUT-1 due to the presence of activating mutations in KRAS (Ki-ras2 Kirsten rat sarcoma viral oncogene homolog) or BRAF (B-Raf proto-oncogene, serine/threonine kinase) oncogenes." (PMID 30695991, 2019). "KRAS is a common canonical mutation in colon cancer, distributed among the various CMS." (PMID 29652830, 2018). "Metabolic aberrations might also be important in solid malignancies since KRAS mutations found in resistant colon cancer and NSCLC xenografts were associated with reprogrammed metabolic pathways." (PMID 29184971, 2018). "However, MHYs appear to be incompatible to the colon cancer with RAS mutations because MHYs suppressed the growth of colon cancer cells with only wild-type KRAS." (PMID 30158525, 2018). "Indeed, mutations in the KRAS gene have been recurrently unveiled in numerous neoplasias comprising lung, pancreatic and colon carcinomas, where we have previously found a significant downregulation of CBX7 expression." (PMID 28259135, 2017).
colon carcinoma (continued). "Since in the initial experiments VLX60 was found most active against a cell line from colon cancer we included colon cancer models able to associate the activity to the KRAS and BRAF mutation status, established to have predictive and/or prognostic importance in this tumor type." (PMID 28415818, 2017). "However, common colon cancer cell lines such as SW480 have KRAS mutations and NF-κB signaling cascades that are initiated by phosphati-dylinositol 3-kinase (PI3K)/Akt pathways during tumorigenesis." (PMID 28177885, 2017). "This suggests that the combination of RT11-i and an anti-EGFR antibody might be an effective clinical strategy for patients with advanced colon cancer harbouring oncogenic KRas mutations." (PMID 28489072, 2017). "Finally, we tested the clinical applicability of our approach for detecting KRAS mutations directly in colon tumour tissue sections." (PMID 28094784, 2017). "This pilot aimed to apply word frequency analysis and a naive Bayes classifier on radiology reports to extract distinguishing imaging descriptors of wild-type colon cancer patients and those with v-Ki-ras2 Kirsten rat sarcoma viral oncogene homolog (KRAS) mutations." (PMID 28869500, 2017). "This study investigated whether the survival benefit observed in patients with colon cancer using aspirin could be associated with BRAF or KRAS mutational status." (PMID 28125730, 2017). "The fact was that the xenograft model of colon cancer may induce the transcription of both KRAS and ERK of lung tissues, which may reduce the risk of colon cancer metastasis and wish to provide help for further research." (PMID 28165459, 2017). "Therefore, the antiproliferative activity of the combined cetuximab/celecoxib treatment in colon cancer cells is strongly dependent on the mutational status of KRAS." (PMID 28423516, 2017). "In particular, Fariña-Sarasqueta and colleagues investigated the value of BRAF, microsatellite instability (MSI) and KRAS mutations on clinical outcome of 106 stage II colon carcinoma patients undergone surgery and 258 stage III patients treated with 5-fluorouracil chemotherapy." (PMID 27099668, 2016). "In addition, progression of a previously present KRAS mutated colon carcinoma due to stimulated ERK signaling was reported in a patient with a melanoma treated with dabrafenib." (PMID 26786320, 2016). "Therefore, in this study, we characterized the PI3KCA and KRAS mutational status of several human colon cancer cell lines." (PMID 26715098, 2016). "The KRAS gene had been shown to be expressed and mutated in colon cancer." (PMID 27880931, 2016). "Commonly used colon cancer cell lines frequently contain mutations in KRAS/BRAF." (PMID 27351224, 2016). "Mutations in a gene called KRAS are common in many types of cancer including colon cancer." (PMID 27845624, 2016). "Mutated KRAS oncogene was identified in multiple types of cancers, such as colon cancer (35%–45%)." (PMID 27449290, 2016). "Smoking‐induced KRAS mutations have been found in lung, pancreatic, and colon cancers 24, 25, 26, and a similar mechanism of oncogenesis might be applicable to borderline tumors." (PMID 26762486, 2016). "To understand the importance of PI3K signaling in KRAS mutated colon cancer, we selected human colon cell lines based on mutation status of KRAS and PI3K genes Cell proliferation was measured using the CCK‐8 assay after a 48 h incubation with BKM120, cetuximab, or a combination of both." (PMID 26715098, 2016). "The prognostic role of KRAS mutations in resectable colon cancer remains until now controversial." (PMID 25956750, 2015).
colon carcinoma (continued). "Based on in vitro experiments showing that KRAS mutation is a predictor of oxaliplatin sensitivity in colon cancer cells, it has been suggested that mutant KRAS CRC patients might benefit more from receiving first-line oxaliplatin-based regimens." (PMID 25888291, 2015). "In Japanese population, KRAS gene mutation is found in 30–42% of colon cancer patients." (PMID 25936694, 2015). "Importantly, deletion of mutant KRAS allele in colon cancer cell lines dramatically reduces cellular proliferation, highlighting the fact that many tumors harboring mutant KRAS are KRAS-dependent." (PMID 26024321, 2015). "Colon tumours with a KRAS mutation are less likely to present microsatellite instability." (PMID 26222184, 2015). "KRAS is mutated in 30% of all human cancers, and in 50% of colon carcinomas." (PMID 24962990, 2014). "HER2 was overexpressed in colon tumors harboring KRAS mutations in 5.3% of cases (10 of 188 cases)." (PMID 24668895, 2014). "In these recently published studies, we demonstrated that KRAS gene mutation in mCRC might be a predictor of oxaliplatin sensitivity not only in colon cancer cells but also in mCRC patients." (PMID 24505265, 2014). "A combination of 5-FU and c-Met targeting might be a feasible strategy in malignant colon cancers with KRAS mutations." (PMID 25427200, 2014). "Besides in pancreas and colon cancer, KRAS mutations occur very frequently in non-small cell lung cancer (NSCLC) (15-50%)." (PMID 24368337, 2014). "Particularly, approximately 30%–40% of colon cancers carry a KRAS mutation." (PMID 25713627, 2014). "Second, we showed that CIP2A is downregulated after inhibiting the MAPK pathway in three colon carcinoma cell lines; downregulation in cell lines harbouring a KRAS mutation (HCT116, SW620) is more pronounced than in Caco2 not harbouring a MAPK-pathway mutation." (PMID 24098375, 2013). "To test the method in a diagnostic setting involving cytology preparations, we prepared tumor imprint slides from eight prospective fresh colon cancer specimens with unknown KRAS mutation status, and subjected them to multiplex KRAS in situ mutation detection." (PMID 24280411, 2013). "Finally, among cetuximab-treated patients with AREG-low tumours, those with mutant KRAS fared significantly better than patients harbouring colon cancer with KRAS wild type (81% decreased risk of death)." (PMID 23374602, 2013). "Also, when stratified by KRAS status, a worse colon cancer-specific mortality associated with a PIK3CA mutation was only found in KRAS wild-type tumors." (PMID 24759962, 2013). "For example, Demory Beckler and colleagues detected KRAS in exosomes released by colon cancer cells and showed that the mutated KRAS can alter the signals induced by cells via exosomes, leading to a growth advantage in the recipient non-transformed wild-type KRAS-expressing cells." (PMID 23466882, 2013). "In particular, approximately 30%–40% of colon cancers harbor a KRAS mutation." (PMID 23202889, 2012). "For instance, KRAS activating mutations are present in approximately 35–50% of colon cancers." (PMID 23227266, 2012).